AMH (anti-Mullerian hormone)
Diseases named in the same sentence as AMH in open-access papers (continued):
Sharing a sentence is not in itself a finding about the gene and the disease.
Miscarriage (22 papers, 2014 to 2025). A pregnancy that ends at a stage in which the fetus is incapable of surviving on its own, defined as the spontaneous loss of a fetus before the 22th week of pregnancy. "Prior studies have reviewed AMH’s ability to predict live birth and miscarriage and have found it is inversely associated with miscarriage in naturally conceived pregnancies." (PMID 37020210, 2023). "This conclusion was inconsistent with that of another recent study, which suggested both age and the AMH level as risk factors of miscarriage." (PMID 31311571, 2019). "In the univariate model, lower age, lower number of previous miscarriages, and higher AMH levels were associated with an increased chance of a future live birth." (PMID 30357497, 2019). "We correlated Anti-Mullerian hormone (AMH) levels and other parameters for ovarian reserve to the gestational age at the time of pregnancy loss in women with idiopathic recurrent miscarriage." (PMID 28768516, 2017). "Recent studies tried to find out whether AMH had an association with reproductive outcomes, including rate of oocyte collected, clinical pregnancy, live birth, and miscarriage." (PMID 35813637, 2022). "These aims could be achieved: We were able to demonstrate that IRM was associated with lower basal estradiol and AMH levels compared to explained recurrent miscarriage." (PMID 27627119, 2016). "Although it might not be the case that anembryonic/empty sac miscarriages or yolk sac miscarriages are those with the highest aneuploidy rates, our data clearly suggest that a higher biological age, as indicated by lower AMH levels, was associated with very early types of pregnancy losses." (PMID 28768516, 2017). "This study was not powered to detect a difference in pregnancy outcomes, yet this is in line with other studies on the impact of AMH on reproductive outcome in BRCA carriers where reproductive outcomes in terms of miscarriage and live birth rates were similar." (PMID 35705781, 2023). "This study adds clarity to the mixed findings of prior studies that have examined the relationship between AMH and miscarriage in ART cycles." (PMID 37020210, 2023). "The miscarriage rate was significantly higher in low-AMH group compared with average- and high-AMH groups (18.0% vs. 12.9% vs. 12.7% respectively; P = 0.024)." (PMID 35236324, 2022). "In patients younger than 35 years, significant differences between AMH subgroups were detected in clinical pregnancy per transfer (p = 0.003), miscarriage per clinical pregnancy (p = 0.015) and ongoing pregnancy per transfer (p = 0.001)." (PMID 33673814, 2021). "AMH is both a gonadal hormone and a putative paracrine regulator of neurons, the uterus, and the placenta, and high AMH levels can lead to miscarriage phenotypes in mouse model studies." (PMID 34956097, 2021). "Through univariate and multivariate logistic regression analysis, it was shown that female age, male age, basic FSH, AMH and the number of fetuses at pregnancy diagnosis influenced spontaneous abortion." (PMID 34059771, 2021). "It is also observed a correlation between miscarriages with serum levels of AMH that can be explained by increased rate of fetal aneuploidy indirectly related to the embryo score." (PMID 35761734, 2014). "Some studies have noted similar findings, low AMH of 0.08–1.6 ng/ml, being associated with miscarriage independent of age in IVF cycles." (PMID 37020210, 2023). "When AMH > 11.6 ng/mL, the incidence of miscarriage is OR 1.1; 95% 1.0–1.1; P = 0.124." (PMID 34059771, 2021). "When AMH ≤ 3.1 ng/mL, the incidence of miscarriage is OR 0.8; 95% 0.7–0.8; P < 0.001." (PMID 34059771, 2021). "When 11.6 ng/mL ≥ AMH > 3.1 ng/mL, the incidence of miscarriage is OR 1.0; 95% 1.0–1.0; P = 0.365." (PMID 34059771, 2021). "At the same time, most studies of this issue have failed to account for other risk factors for miscarriage that are influenced by age and DOR, such AMH, AFC and FSH." (PMID 33819190, 2021).
Miscarriage (continued). "The smooth curve fit showed that female age, male age, and basic FSH were positively correlated with miscarriage and that AMH had a negative correlation with miscarriage." (PMID 34059771, 2021). "In our study, several reproductive markers, such as AMH, AFC, basal FSH level, the number of oocytes retrieved and previous reproductive history, including prior gravidity and miscarriage, were significantly different between young and old patients with DOR in our study." (PMID 33819190, 2021). "AMH seems of either no or only minor relevance for the prediction of further miscarriages and live birth in women with idiopathic recurrent miscarriage." (PMID 30357497, 2019). "In the multivariate analysis, only age (OR 0.920, 95% CI 0.859–0.986; p = 0.019) and the number of previous miscarriages (OR 0.403, 95% CI 0.193–0.841; p = 0.016), but not AMH (OR 1.191, 95% CI 0.972–1.461; p = 0.091), remained statistically significant." (PMID 30357497, 2019).
Premature ovarian insufficiency (21 papers, 2014 to 2026). Amenorrhea due to loss of ovarian function before the age of 40. "Hormonal exams, performed at the same age and repeated 6 month later, were diagnostic for early hypergonadotropic hypogonadism and AMH values confirmed the diagnosis of primary ovarian insufficiency at a very early age." (PMID 37383390, 2023). "Hormonal exams, performed at 9 years and 11 months of age, were diagnostic for early hypergonadotropic hypogonadism and AMH values confirmed the diagnosis of premature ovarian insufficiency." (PMID 37383390, 2023). "There is a general agreement that age, endometrioma bilaterality, and previous ovarian surgery are key risk factors for significant serum AMH reduction and the threat of premature ovarian insufficiency in women undergoing endometriotic cystectomy." (PMID 36213292, 2022). "The purpose of this systematic review and network meta-analysis is to evaluate the role of serum anti-Müllerian hormone (AMH) for ovarian reserve screening and the risk of premature ovarian insufficiency (POI) according to the subtype of childhood cancer." (PMID 34944951, 2021). "That is why only a huge reduction of AMH could be considered of clinical relevance in woman aged 35 years old who may determine the consideration of these woman as at risk of premature ovarian insufficiency and this was excluded by this study." (PMID 31147558, 2019). "In oncology patients, AMH can be serially measured to assess the impact of chemotoxic agents on ovarian function, to forecast future fertility and the onset of premature ovarian insufficiency." (PMID 35869476, 2022). "Measurement of anti-Müllerian hormone (AMH), produced by granulosa cells of growing follicles, is widely used as a marker of ovarian reserve and has a potential as a diagnostic and predictive biomarker of premature ovarian insufficiency (POI)." (PMID 41153822, 2025). "However, at the same age, serum AMH values were still in the lower range, possibly suggesting a early-stage primary ovarian insufficiency (POI)." (PMID 37383390, 2023). "Serum AMH level is a representative marker of ovarian aging and ovarian reserve in human, and is commonly used to assess extent of ovarian follicle depletion, to diagnose premature ovarian insufficiency, and to predict age at menopause." (PMID 33888135, 2021). "Mice lacking AMH exhibit early follicular recruitment and loss, and AMH sequence variants in humans have been associated with premature ovarian insufficiency (POI)." (PMID 32404103, 2020). "Another study suggested that supplementation with vitamin E can increase the level of the anti-mullerian hormone (AMH), antral follicle count, and mean ovarian volume in women with occult premature ovarian insufficiency (POI)." (PMID 36387403, 2022). "Studies have demonstrated increases in retrieved oocyte numbers, elevated anti-Mullerian hormone (AMH) levels, reduced follicle-stimulating hormone (FSH) concentrations, and trends toward improved clinical pregnancy and live birth rates in women with premature ovarian insufficiency." (PMID 41226837, 2025). "On the other hand, recent evidence shows that neither single AMH measurements nor AMH trajectories adds significant precision to models that aim to predict menopause, except in the few cases where primary ovarian insufficiency is diagnosed early." (PMID 41030482, 2025).
cyst (19 papers, 2014 to 2025). A sac-like closed membranous structure that may be empty or contain fluid or amorphous material. "In a series of 332 patients with endometriosis, a cyst size of over 6 cm was significantly associated with higher AMH levels." (PMID 36902645, 2023). "The present study outcomes showed that, the serum level of AMH decreases significantly after cystectomy, and this decrease can be associated with factors such as the type of cyst, the type of involvement, and the number of cauterizations used during the operation." (PMID 36120464, 2022). "The median AMH concentrations were 3.03 (IQR 3.61) ng/ml for those with a unilateral cyst and 2.71 (IQR 2.93) ng/ml for patients with bilateral cysts, demonstrating a statistically significant difference (p=0.041)." (PMID 38562412, 2024). "When expectant management is decided upon, it seems wise to evaluate with serial measurements both the cyst size and the ovarian reserve, either with AMH or AFC." (PMID 36902645, 2023). "There was a significant relationship between the location (p ≤ 0.01), type of cyst (p ≤ 0.001) and the serum AMH levels reduction." (PMID 36120464, 2022). "The impact factors include laterality, pre-operative AMH levels, age and size of the cyst 12, 14, 23, 29-31." (PMID 35582413, 2022). "The number of cauterizations used during surgery, the type of cyst, and bilaterality can affect AMH levels that need to be addressed." (PMID 36120464, 2022). "As the secondary outcome of the present study, there was a significant relationship between the number of cauters used, the location (unilateral or bilateral), and the type of cyst with the amount of serum AMH level drop." (PMID 36120464, 2022). "It was claimed that with increasing cyst size, the amount of serum AMH level in the third month after surgery would be significantly reduced." (PMID 36120464, 2022). "They reported that AMH levels gradually decreased in patients with bilateral tumors or those with cyst diameters ≥5 cm." (PMID 27793163, 2016). "For evaluation of primary cyst size effect on AMH variation after cystectomy patients were categorized as follows: Group 1) cyst size 40-65 mm, Group 2) cyst size 65-90 mm, Groups 3) cyst size larger than 90 mm." (PMID 26000005, 2015). "It is not known whether all women with PCOS secrete the same amount of AMH per cyst, but it is unlikely." (PMID 36766605, 2023). "Bilateral endometriomas, size of the cyst, and preoperative AMH levels might independently affect AMH levels at 12 months after surgery." (PMID 35582413, 2022). "The factors that may affect AMH levels at 12 months after surgery are bilateral endometriomas, mean size of the cyst and preoperative AMH levels." (PMID 35582413, 2022). "There was a significant difference between cyst type and a decrease in serum AMH level (p ≤ 0.001)." (PMID 36120464, 2022). "Based on multivariate regression, only bilateral localization of ovarian endometrial cyst (p = 0.003) and patient age (p < 0.001) but not localization or cyst volume were negatively associated with the AMH serum concentration." (PMID 26596960, 2015). "The study population was categorized regarding age, primary cyst size and primary AMH level." (PMID 26000005, 2015). "Based on a multivariate regression analysis, only bilateral localization of ovarian endometrial cysts (p = 0.003) and patient age (p < 0.001), but not left/right localization of unilateral cyst or cyst volume, were negatively associated with AMH serum concentration." (PMID 26596960, 2015). "Preoperative anti-mullerian hormone (AMH) levels were measured and unilateral antral follicle counts (AFC) were calculated for the ovary side containing the cyst." (PMID 32341825, 2020). "Data on the effect of patient age and cyst size on the decline of AMH levels at the time of surgery are not consistent in the current literature." (PMID 36902645, 2023).
cyst (continued). "The results surprisingly revealed significant difference between AMH level decline in dermoid cyst and the two other studied cyst types but no variation among mucinous and serous cystadenomas was observed." (PMID 26000005, 2015). "However, factors such as prior nongynecological abdominal surgeries or cyst ruptures did not affect AMH levels." (PMID 38562412, 2024). "Notably, cyst size did not correlate with AMH reductions, consistent with findings from Somigliana and Hirokawa." (PMID 38562412, 2024). "Moreover, significant negative correlation exists between LE and AMH concentration in the cyst wall of ovarian endometrioma (P<0.001)." (PMID 37370122, 2023).
Ovarian cyst (18 papers, 2010 to 2025). The presence of one or more cysts of the ovary. "The multiple surgeries the patient in case I had to remove the ovarian cysts are the likely culprit in the loss of ovarian reserve, as seen by her abnormally low AMH level and poor response." (PMID 39039557, 2024). "Our reproductive phenotyping indicates that the ovary is the primary site of dysfunction, in which Ubc9fKO females exhibit irregular estrous cycles, lowered AMH, reduced ovulatory capacity, and large ovarian cysts." (PMID 41206127, 2025). "We excluded women with ovarian cysts or follicles >25 mm when presenting the results for ovarian volumes, AFCs, and AMH levels." (PMID 41030482, 2025). "The pretreatment AMH level are significantly lower in cases of bilateral ovarian cysts compared to unilateral, and the posttreatment decline in AMH is more pronounced." (PMID 38562412, 2024). "But in general, the results of the present study are in line with and previously published studies (a total of more than 30 studies with more than 1200 participants) showed a significant reduction in serum AMH level after laparoscopy of ovarian cysts." (PMID 36120464, 2022). "The results of our study also revealed greater decline in AMH level in the group of cases whose primary ovarian cyst size was larger than 90mm versus those with 45-60 mm cysts." (PMID 26000005, 2015). "As table I implies, within each type of ovarian cysts, variations (primary decline and long term elevation) of serum AMH levels were significant (p<0.001)." (PMID 26000005, 2015). "Serum AMH levels were compared before and after the surgery and between various types of ovarian cyst." (PMID 26000005, 2015). "Three months later, breast development decreased, the ovarian cyst disappeared, the plasma concentration of estradiol decreased to <37 pmol/l, while AMH was 25 pmol/l and inhibin B <10 pg/ml." (PMID 20593028, 2010). "Moreover, the time between litters lengthened with age in Ubc9fKO females, likely reflecting progressive ovarian decline, consistent with diminished AMH and the presence of ovarian cysts." (PMID 41206127, 2025). "The Induction of PCOS led to a significant increase in body and ovarian cyst weight, elevated serum levels of testosterone, luteinizing hormone (LH), and anti-Müllerian hormone (AMH), alongside reduced follicle-stimulating hormone (FSH) and progesterone levels." (PMID 39286642, 2024). "We also investigated the difference in AMH concentration between endometriomas and non-endometrioma ovarian cysts and the association between AMH and fertility outcome." (PMID 38562412, 2024). "Serum anti-Mullerian hormone (AMH) correlates with the number of ovarian cysts." (PMID 36766605, 2023). "We also compared the level of AMH before and after the operation within each type of ovarian cyst." (PMID 26000005, 2015). "In the present study we investigated the effect of laparoscopic ovarian cystectomy on serum AMH in patients with three most common types of ovarian cysts (Dermoid cyst, serous and mucinous cystadenoma) in Shiraz Zeinab Hospital, an affiliated center to Shiraz University of Medical Sciences." (PMID 26000005, 2015). "It has been claimed that womenwith endometriomas have lower levels of anti-Müllerian hormone (AMH) andantral follicle counts (AFC) compared to women without ovarian cysts, suggestingthat the presence of endometrioma is associated with a reduction in ovarian reserve." (PMID 36749809, 2023). "If some cysts secrete larger amounts of AMH and AMH causes resistance to FSH in the follicle, it is conceivable that even if two women have the same number of ovarian cysts, the woman with the higher serum AMH level may have more reproductive problems than the one with the lower serum AMH level." (PMID 36766605, 2023). "Assessment of ovarian reserve revealed a significant decrease in the level of serum AMH and a significant increase in AFC after our novel technique in surgical treatment of ovarian cysts." (PMID 35787807, 2022).
Ovarian cyst (continued). "We also analyzed subgroups consisting of pre- and 3-month post-surgery AMH levels by comparing control and TXA groups for each unilateral and bilateral ovarian cyst group." (PMID 34481524, 2021). "Pretreatment AMH levels did not significantly differ between patients with endometriomas and those with non-endometrioma ovarian cysts." (PMID 38562412, 2024). "The prospective analysis of AMH levels prior to treatment in patients with OEM and other ovarian cysts suggests that OEM have no significant impact on pretreatment AMH levels compared to the control group." (PMID 38562412, 2024). "Assessment of ovarian reserve revealed a significant decrease in the level of serum AMH (2.82 ± 0.44 vs. 2.50 ± 0.42) and a significant increase in AFC (3.5 ± 1.7 vs. 4.9 ± 1.3) after our novel technique in surgical treatment of ovarian cysts (P value < 0.001)." (PMID 35787807, 2022). "When performing a subgroup analysis, the mean difference of AMH levels (pre- and 3 months post-surgery) seemed to be higher in the bilateral than in the unilateral ovarian cyst group but not significantly different." (PMID 34481524, 2021). "A 2018 meta-analysis evaluating AMH levels in unoperated patients with endometriotic ovarian cysts reported up to 26% lower AMH values in patients with endometriomas compared to a control group of patients with ovarian cysts of other etiology and patients without ovarian pathology." (PMID 39044926, 2024). "Anti-Müllerian hormone (AMH) levels and other clinical data from 233 patients with endometriomas and 57 patients with non-endometrioma ovarian cysts admitted to the Peking Union Medical College Hospital between January 2018 and September 2023 were prospectively analysed." (PMID 38562412, 2024). "As a marker for ovarian reserve, MIS/AMH correlates positively with ovarian response to COH in normoovulatory women, but in poly cystic ovary patients (PCOS) AMH may not be an accurate predictor for pregnancy." (PMID 25242994, 2012). "The mean difference of AMH levels in the TXA and control groups in women with unilateral ovarian cyst was not significantly different (0.06, 95%CI − 0.86 to 0.98)." (PMID 34481524, 2021). "The mean difference in AMH levels in the TXA and control groups in women with bilateral ovarian cyst was not significantly different (0.22, 95%CI − 0.98 to 1.42)." (PMID 34481524, 2021).